BMP2 (bone morphogenetic protein 2)
Diseases named in the same sentence as BMP2 in open-access papers (continued):
Sharing a sentence is not in itself a finding about the gene and the disease.
osteoporosis (continued). "Our peptide utilizes the BMP pathway in both skeletal diseases and induces an osteogenic response; therefore, it has greater therapeutic potential for osteoporosis, especially over BMP2." (PMID 31771161, 2019). "The aim of the study presented here was to compare the responsiveness of osteoblasts to bone morphogenetic protein 2 and casein kinase 2.3, especially in patients diagnosed with osteoporosis." (PMID 31771161, 2019). "Studies that were done on current treatments of osteoporosis such at BMP2 and PTH showed that long-term usage of these compounds resulted in enhancing osteoclast differentiation and bone resorption." (PMID 30294717, 2018). "Our results explained, at lease in part, the reduced responsiveness of osteoporotic MSCs to BMP2, and suggested a new therapeutic strategy to improve the clinical efficacy of BMP2 for the treatment of osteoporosis." (PMID 27512956, 2016). "There are studies which reported that statins were able to increase bone formation and has potential for the treatment of osteoporosis and its complications by stimulation of bone morphogenetic proteins-2 (BMP-2)." (PMID 25526611, 2014). "Factors thought to contribute to cage subsidence are the narrower 18 mm cages, osteoporosis, the use of BMP-2, the use of standalone cages, and iatrogenic endplate violation." (PMID 23213282, 2012). "Thus, increased expression of BMP-2 prevents loss of BMD from the bone and protects the bone from ovarian deficiency-induced osteoporosis." (PMID 39254876, 2025). "The rationale behind the use of statins to reduce osteoporosis and fractures stems from reports showing that statins can stimulate the production of bone morphogenetic protein-2 (BMP-2), which promotes the differentiation of osteoblasts, the cells responsible for bone formation." (PMID 40688824, 2025). "In this study, we hypothesized that antiresorptive bisphosphonates (BPs) could serve as an ion-pairing counterpart to control and prolong the release of BMP2 via electrostatic interaction, thereby enhancing its therapeutic potential for osteoporosis." (PMID 40987998, 2025). "In this context, the hypothesis emerges that rosavin may influence BMP-2 expression in human osteoblasts (HOBs), thereby opening new therapeutic possibilities for the treatment of osteoporosis and other metabolic bone diseases." (PMID 40649853, 2025). "Additionally, aucubin facilitated osteogenic differentiation of hBMSCs by activating the BMP2/SMADs pathway and attenuated the progression of osteoporosis in OVX rats, suggesting a potential therapeutic benefit for postmenopausal osteoporosis (PMOP)." (PMID 39823248, 2025). "BST2 regulates BMP-2 pathway and therefore any negative effects will disrupt the osteogenic process and potentially cause osteoporosis." (PMID 39497989, 2024). "The osteoprotective properties of RSV through the modulation of RANK/RANKL/OPG, SIRT1, Wnt/β-catenin, MAPKs/JNK/ERK, PI3K/AKT, microRNAs, and BMP2 are discussed in this section as the key mechanisms related with bone remodelling and development of osteoporosis." (PMID 37239124, 2023). "MQEF also exerts an effective protective effect against osteoporosis by enhancing BMP2 levels, promoting the differentiation of bone marrow mesenchymal stem cells (BMSC) to osteoblasts, and increasing serum osteosclerin levels in postmenopausal patients with osteoporosis." (PMID 36034465, 2022). "High levels of OPN could increase matrix deposition and enhance bone remodeling by promoting osteoblasts differentiation along with the elevated level of ALP, OCN, and BMP-2 which finally resulted in reducing the pain and pathological changes of osteoporosis." (PMID 36387862, 2022). "Indeed, the methylation level of the BMP2 promoter has been reported to significantly correlate with the degree of osteoporosis in affected patients, resulting in BMP2 downregulation." (PMID 35163424, 2022).
osteoporosis (continued). "Moreover, our findings propose BMP2 as a potential drug target for the therapy of bone metabolic diseases, such as osteoporosis, based on its roles in osteoclast differentiation." (PMID 35164658, 2022). "For example, it is confirmed that circ-0000020 could promote osteogenic differentiation, retard the progress of osteoporosis, and upregulate the expression of BMP2 via sponging miR-142-5p as ceRNA." (PMID 35992137, 2022). "The use of bisphosphonates in patients with osteoporosis reduces the production of BMP-2, while CGF or treatment with resveratrol combined with CGF instead promotes the production of BMP-2, and they have a positive role on osteoblasts in patients treated with bisphosphonates." (PMID 35161065, 2022). "For example, a study demonstrated that lncRNA MSC-AS1 could inhibit the development of osteoporosis by promoting the osteogenic differentiation of BMSCs via regulating the miR-140-5p/BMP2 axis." (PMID 34772438, 2021). "It was found to prevent osteoporosis and promote BMP2 expression by sponging miR-98." (PMID 33648601, 2021). "Hsa_circ_0016624 prevents osteoporosis and promotes BMP2 expression by sponging miR-98." (PMID 33648601, 2021). "Furthermore, individuals with senile osteoporosis who experience a fracture have lower BMP-2 levels when compared to healthy controls." (PMID 33007863, 2020). "This demonstrates that BMP-2 cannot enhance bone mineral density in patients diagnosed with osteoporosis, but still causes adverse side-effects such as radiculitis, hematoma, and an increased rate of microfractures." (PMID 32933207, 2020). "A specific example is bone morphogenetic protein-2 (BMP-2), which is implicated in aberrant signaling during osteopenia and osteoporosis, however, the mechanism of this pathway is unknown." (PMID 32575709, 2020). "Our results show, for the first time, that KDM5A-mediated H3K4me3 modification participated in the etiology of osteoporosis and may provide new strategies to improve the clinical efficacy of BMP2 in osteoporotic conditions." (PMID 27512956, 2016). "In this study, we wonder whether lysine (K)-specific demethylase 5A (KDM5A) functions as endogenous modulator of BMP2-induced osteogenic differentiation of MSCs in osteoporosis." (PMID 27512956, 2016). "More importantly, our study also revealed the potential of fibrin sealants as an effective carrier for encapsulating anti-osteoporosis drugs (e.g., BMP2 and zoledronate) for improving bone quantity and quality in highly incident fracture regions of osteoporotic animals." (PMID 27329730, 2016). "MSCs are also an attractive cellular vehicle for the in vivo delivery of therapeutic genes, such as the genes encoding BMP-2 and RANK-Fc (a soluble inhibitor of RANKL), which could increase bone formation in osteoporosis animal models." (PMID 28536615, 2016). "We demonstrated that Kdm5a-mediated H3K4me3 modification participates in the etiology of osteoporosis, which may provide new strategies to improve the clinical efficacy of BMP2 and to enhance bone formation under osteoporotic conditions." (PMID 27512956, 2016). "Particularly, the application of genome-wide association scan has allowed the identification of bone morphogenetic protein 2 (BMP2) as a candidate gene for osteoporosis, through the analysis of 207 osteoporotic families (1323 individuals) in Iceland and the subsequent followup association analysis." (PMID 20948561, 2010). "Given the interaction between BMP2 and PDE4 for the inhibition on osteoblastic differentiation in vitro, it is interesting to note that variants in the gene encoding for BMP2 have also been found to increase risk of osteoporosis in humans." (PMID 15752431, 2005). "When osteoporosis occurred, the number of bone marrow mesenchymal stem cells differentiating into adipocytes increases and osteoblast generation decreases; studies have shown that activation of bone morphogenetic protein 2 could inhibit adipogenesis." (PMID 38474436, 2024).
osteoporosis (continued). "The animal model showed that up-regulated OPN could enhance the activity of ALP, OCN, and BMP-2 in dexamethasone-induced OP, the anti-osteoporosis function of myricetin in vivo may be due to the promoting osteogenic differentiation and matrix mineralization effect caused by OPN." (PMID 36387862, 2022). "Similarly, the circRNA-0016624/miR-98/BMP2 axis could prevent osteoporosis and offer a novel insight into therapeutic strategy." (PMID 35992137, 2022). "However, the use of BMP2 for treatment of degenerative bone diseases such as osteoporosis is still uncertain as patients treated with BMP2 results in the stimulation of not only osteoblast mineralization, but also osteoclast absorption, leading to early bone graft subsidence." (PMID 34203252, 2021). "Moreover, the high expression of BMP2 mitigates glucocorticoid-induced osteoporosis." (PMID 34645714, 2021). "Moreover, they found that BMP2 was decreased in osteoporosis group compared to controls." (PMID 34490735, 2021). "Evidence suggests BMP-2 activity may play an important role in the etiology of osteoporosis." (PMID 33007863, 2020). "A clinical trial of simvastatin in postmenopausal female patients with osteoporosis demonstrated the ability of simvastatin to increase new bone formation, while an in vitro study characterized the mechanisms through which simvastatin (2.5 μM) increases expression of the BMP-2 gene in bone cells." (PMID 24039733, 2013). "Regulation of BMP2/RUNX2-mediated molecules, inducing the formation of mineralized bone matrix for osteoporosis treatment by generating new bone matrix." (PMID 40799828, 2025). "Suppression of miR-92b-3p expression increased Nox4 and NF-κB levels, decreased Smad7, BMP2, and RUNX-2 genes and protein expression, and inhibited BMSC proliferation and osteoblast differentiation, resulting in worsened osteoporosis." (PMID 37239124, 2023). "The authors verified the potential anti-osteoporotic effects of apple-derived nanovesicles using MC3T3-E1 cells, inhibiting osteoporosis by promoting osteoblastogenesis in osteoblastic MC3T3-E1 cells, by regulating the BMP2/Smad1 pathway." (PMID 37109395, 2023). "Many signaling pathways, such as BMP-2, Wnt/β-catenin, and VEGF/VEGFR, participate in the biological actions of naringin in mediating the pathological development of osteoporosis." (PMID 37175126, 2023). "Haasters et al23 found MSCs from patients with osteoporosis showed a surge in the migration upon bone morphogenetic protein 2 (BMP‐2) stimulation, as well as their invasion increased significantly upon BMP‐2 or BMP‐7 stimulation." (PMID 33210341, 2021). "The present study determined that expression of osteoblastic markers BMP-2, RUNX2, OSX, ALP, OPN and BSP-1 were significantly decreased in OVX-induced osteoporosis while treating PMT increased those of osteoblastic markers in a dose-dependent manner." (PMID 33841161, 2021). "In 26 postmenopausal women with osteoporosis, and also in ovariectomized mice, there is elevated miR-410 and reduced BMP-2 (bone morphogenetic protein 2) in serum samples." (PMID 32664424, 2020). "NM improved proliferation, ALP activity, mineralization, and expression of osteoblast differentiation markers (BMP-2, p-SMAD 1/5/8, RUNX2, Wnt3a, osteocalcin, and COL-1) in an osteoblastic cell line in vitro and in a model of osteoporosis in vivo." (PMID 32013042, 2020). "The present study also demonstrated that vitamin C enhanced the expression of the osteoblast-specific genes, BMP-2, SMAD1/5/8, RUNX2, osteocalcin, and COL-1, in an in vivo model of osteoporosis." (PMID 30818817, 2019). "We observed earlier protection of local BMP2 delivery from osteoporosis-induced decreases of bone quantity and bone quality than ZOL, and BMP2 plus ZOL exhibited most significant long-term efficiency on resisting bone loss and enhancing the fracture toughness." (PMID 27329730, 2016).
osteoporosis (continued). "used synthetic biology to integrate BMP-2 and CXCR4 onto the surface of bacterial EVs to deliver BMP-2, activating osteogenic signaling and significantly enhancing bone density and strength while inhibiting adipogenesis, thereby improving osteoporosis." (PMID 40761817, 2025). "In the glucocorticoid-induced osteoporosis rat model, the use of Gastrodin was found to improve osteoporosis status by activating the Nrf2/Keap1 pathway and upregulating the expression of OCN, BMP-2, and RUNX2." (PMID 41282615, 2025). "By targeting GREM2 to activate the BMP2/SMAD pathway, miR-671-3p may stimulate osteogenic differentiation, foster bone formation, and prevent the onset of osteoporosis." (PMID 40500779, 2025). "BMP-2 is of critical importance in regenerative therapy and in the treatment of bone disorders, including osteoporosis and non-healing fractures." (PMID 40649853, 2025). "Inadequate TIEG1 expression may lead to osteopenic phenotype in TIEG1 KO mice and osteoporosis in humans, and a recent study found that osteoprotegerin (OPG) and RANKL expression are controlled by Wnt/β-catenin and BMP-2 signaling." (PMID 39371752, 2024). "Circ_0007059 might play a crucial role in osteoclastogenesis via the miR‐378/BMP‐2 signaling pathway, suggesting that targeting the circ_0007059/miR‐378/BMP2 axis could be a novel therapeutic approach for osteoporosis." (PMID 39239069, 2024). "Clinical and preclinical studies have demonstrated the osteoinductive capacity of BMP-2 therapy in several intervention scenarios, such as bone defects, non-union fractures, spinal fusion, root canal surgery, and osteoporosis." (PMID 37373757, 2023). "In conclusion, we identified APPL1 may be an important regulator in osteoporosis, which inhibited the expression of MGP, activated the BMP2 pathway, and promoted the osteogenic differentiation of MSCs." (PMID 37187293, 2023). "However, the BMP-2/Smad/Runx2 signalling cascade activity was reduced in the bone tissues of OVX rats, exacerbating osteoporosis." (PMID 37239124, 2023). "The sustained release of BMP-2 and 17-β-estradiol effectively improved bone defect repair in OP (osteoporosis) rats, but the experiments demonstrated that PRGF did not improve bone repair." (PMID 36986842, 2023). "Anti-Osteoporosis Decoction (AOD) and Yougui Pill treatment effectively inhibits osteoporosis and reduces the broken trabecular bones, increases the level of BMD, ALP levels, accompanied by the increased expressions of BMP2, Runx2, Collagen I and OPN." (PMID 36387862, 2022). "In addition, the combined application of bone morphogenetic protein 2 (BMP2) and methyltransferase EZH2 inhibitors optimized the therapeutic effect on osteoporosis." (PMID 35578312, 2022). "Regarding osteoporosis, use of BMP-2 has not been FDA approved due to having a short half-life and issues with systemic administration." (PMID 33007863, 2020). "Synthesized peptides, such as Romosozumab and CK2.3, promote osteoblastogenesis and limit osteoclastogenesis, making them possible therapeutics for osteoporosis by BMP-signaling without exogenous BMP-2." (PMID 32933207, 2020). "Recent data have shown that cells extracted from patients diagnosed with osteoporosis do not respond to BMP-2 stimulation, whereas cells extracted from patients diagnosed with osteoarthritis are still responsive." (PMID 32933207, 2020). "In addition, taurine increased the expression levels of BMP-2, Wnt3a, SMAD1/5/8, RUNX2, and COL-1 in the in vivo osteoporosis model and stimulated the p-Akt, p-p38, p-JNK, and p-ERK signaling pathways." (PMID 31970094, 2019). "In addition to the importance of BMP2 development, recent research has shown a potential BMP signaling disparity in those diagnosed with osteoporosis." (PMID 31771161, 2019). "Some groups have observed a decrease in BMP2-activated BMP canonical signaling in primary bone marrow stromal cells (BMSCs), which is a possible explanation for the decrease in bone formation observed in osteoporosis." (PMID 31771161, 2019).
osteoporosis (continued). "Furthermore, these Ca extracts increased the expression levels of BMP-2, Wnt3a, SMAD5, RUNX2, osteocalcin and COL-1 in an in vivo model of osteoporosis, while they decreased TRAP, cathepsin K and RANK expression levels." (PMID 28513557, 2017). "We have shown that KLEXJ boosts ALP activity and BMP-2 production in osteoblasts via the PI3K/Akt-NF-κB pathway and hence may be suitable in the treatment of osteoporosis." (PMID 28474578, 2017). "Furthermore, local administration of DQ combined with bone morphogenetic protein 2 (BMP-2), a known osteoinductive agent, showed synergistic effects on bone regeneration, confirming the efficacy of DQ in the treatment of post-menopausal osteoporosis." (PMID 39335461, 2024). "The phenols from areca nut seed was reported that it could relieve osteoporosis through regulating the expression of osteoprotegerin (OPG), RANKL, LDL-receptor relater protein 5 (LRP5), bone morphogenetic protein-2 (BMP2) and β-catenin related to the Wnt/β-catenin pathway in VOX-induced OP rats." (PMID 39449745, 2024). "Suppression of miR-92b-3p expression increased NADPH oxidase 4 (Nox4) and NF-κB levels, decreased Smad7, BMP2, and Runx2 gene and protein expressions, and inhibited bone marrow mesenchymal stem cell (BMSC) proliferation and osteoblast differentiation, resulting in more severe osteoporosis." (PMID 37239124, 2023). "Preclinical data, efficacy, and feasibility of studies in animals served as backbones for the clinical trials that intend to use recombinant human BMP-2 (rhBMP-2) for several bone diseases, such as: bone defects, non-union fractures, spinal fusion, root canal surgery, and osteoporosis." (PMID 37373757, 2023). "The traditional Chinese medicine mainly targeted to increase the expression of OPN, BMP-2 and Runx2 which finally resulted in reducing the broken trabecular bones in femur bones and increasing the activity of ALP combined with enhanced the content of total bone mineral density in osteoporosis rats." (PMID 36387862, 2022). "The study conducted in osteoporosis rats showed that the overexpression of BMP-2 in rat bone marrow mesenchymal stem cells (rBMSCs) activates the BMP signaling pathway promoting osteoblastic differentiation, while the low expression of BMP-2 suppresses the BMP signaling pathway in rBMSCs." (PMID 34360948, 2021). "As a result, BMP-2 may not be useful for treating osteoporosis, and alternative therapeutics are desperately needed (described in the next section)." (PMID 32933207, 2020). "In our study, JGSQP activated the expression of p-AKT along with multiple bone formation and adipogenesis-related genes (Wnt10b, Osx, BMP2, PPARγ, Fabp4, and Fndc5), suggesting that it may ameliorate murine OVX-induced osteoporosis with KYD by controlling the bone-fat balance via the AKT pathway." (PMID 32963560, 2020). "Other studies also show that Mg can enhance the expression of some growth factors, such as bone morphogenetic protein-2 (BMP-2) and vascular endothelial growth factor (VEGF), which could promote bone formation and be beneficial for reducing the harmful effect of osteoporosis." (PMID 29895809, 2018). "Thus, KLEXJ enhances ALP activity and BMP-2 production of osteoblasts through the PI3K/Akt/ NF-κB signaling pathway and hence may be suitable in the treatment of osteoporosis." (PMID 28474578, 2017). "Given the prevalence of T1DM-related osteoporosis and the lack of safe and effective anabolic therapies, studying a corollary between BMP-2 and its possible effect on T1DM-related osteoporosis seems like a natural progression to a potentially beneficial clinical modality." (PMID 25421865, 2015). "The flavonoids of Rhizoma Drynariae (RDF) have a clear preventive and therapeutic effect on osteoporosis (OP), but it is not yet clear whether RDF has an anti-DOP and whether its mechanism is related to the activation of the BMP2/Smad signaling pathway." (PMID 36825725, 2023).